TNF (tumor necrosis factor)
Diseases named in the same sentence as TNF in open-access papers (continued):
Sharing a sentence is not in itself a finding about the gene and the disease.
lung carcinoma (continued). "EGCG loaded with poly(lactic-co-glycolic acid) (PLGA) nanoparticles suppressed the NF-κB pathway and inhibited the mRNA expression of several downstream molecules, such as MMP-2, cyclooxygenase-2 (COX-2), and tumor necrosis factor α (TNF-α), in the lung cancer cell lines A549 and H1299." (PMID 39335164, 2024). "The levels of inflammatory factors such as IL-1β, IL-6, TNF-α, and CRP in the serum of the lung cancer mice increased, promoting the activation of inflammatory cells and stimulating the release of inflammatory mediators, leading to an increased risk of systemic inflammatory response." (PMID 39594117, 2024). "Moreover, the combination of TNF-α, MIP-1α and MIP-1β are also potential predictors for the early diagnosis of lung cancer." (PMID 38813211, 2024). "However, when combined with TNF-α and IFN-γ, the combination of these five pyroptosis-related cytokines exhibited higher sensitivity (96.9 %) and specificity (93.7 %) for lung cancer compared to individual markers." (PMID 38813211, 2024). "During phenotypic conversion of lung adenocarcinoma, patients who transformed to small cell lung cancer exhibit significant downregulation of the TNF pathway compared to patients who never‐transformed non‐small cell lung cancer." (PMID 39473903, 2024). "Pretreatment with DEX before the induction of general anesthesia (GA) was reported to protect lung cancer patients against lung injury during OLV by upregulating the expression of heme oxygenase-1 and reducing the serum production of TNF-α and reactive oxygen species." (PMID 36765695, 2023). "Notably, among them (IL1-β, IL-3, MCP-1, TNF-α), the EGF, the most acknowledged target for lung cancer therapy, emerges." (PMID 36733673, 2023). "It is hypothesized that TNF-, IFN-, TGF-, VEGF, and interleukins are some of the most important cytokines involved in the pathogenesis of lung cancer and might potentially serve as biomarkers for diagnosis, prognosis, and evaluation of treatment response." (PMID 37373987, 2023). "Interestingly, we very recently also observed an expression of RELA in lung cancer stem cell-like cells (LCSC-like cells), which can be stimulated by applying TNF-α." (PMID 36879191, 2023). "Although this report did not study the role of TNF-α inhibition with immune checkpoint-based therapy, a brief discussion is warranted given the current treatment landscape for lung cancers." (PMID 36241629, 2022). "In particular, TLR9 activation in lung cancer epithelial cells increased the release of TNF-α, but not of IL-6, through an imbalance of the ceramide/S1P rheostat in favor of S1P." (PMID 36010601, 2022). "Anti-TNF-α agents have posed no additional safety issues when given to persons with lung cancers and in patients with other solid tumors receiving chemotherapy." (PMID 36241629, 2022). "Likewise, lung cancer cells activate macrophages via TLR2/6 and 9 to produce TNF-α and IL-6 resulting in a rapid metastatic progress." (PMID 34476575, 2021). "GO and KEGG analyses indicated that the immunoreaction against lung cancer by ginseng leaves might be related to response to lipopolysaccharide, response to oxidative stress, PI3K-Akt, MAPK and TNF pathway." (PMID 34521875, 2021). "Although, no statistically significant changes in IL-6 and TNF-α levels are found between any group of lung cancer patients (adenocarcinoma, SqCC, other NSCLC, and other neoplasms than NSCLC), there are slightly higher levels of IL-6 in SqCC patients." (PMID 34439874, 2021). "Deregulation of TGFbeta signaling has been correlated with EMT transition, cell migration and invasion in lung cancer whereas TNF signaling is being expected playing a major role in inflammation-induced cancer and disturbances in the RAS signaling in lung cancer are long known." (PMID 33596996, 2021). "TNF may also play an important role in mediating resistance to targeted inhibition, particularly in the context of EGFR inhibition in GBM and lung cancer." (PMID 33373873, 2021).
lung carcinoma (continued). "Interestingly, some studies have indicated that TNFα cooperates with RAS in promoting metastasis in at least breast and lung cancers." (PMID 34966481, 2021). "To further investigate the underlying mechanism, we first examined the phosphorylation status of LATS at hydrophobic motif, which is essential for LATS kinase activity using anti-phospho LATS1-T1079/LATS2-T104 antibody in TNF-stimulated HEK293A, NIH3T3, and lung cancer cell A549." (PMID 33571521, 2021). "Data from Gene Expression Profiling Interactive Analysis (GEPIA) 25 analysis confirmed a significantly positive correlation of MARCKS expression with TNFR, RELA, BCL2A1, CXCL1, RELB or TNF-alpha in lung cancer samples but not in normal lung tissues." (PMID 33754052, 2021). "The BCG+ KLN205 (KLN205 cancer cell injection after BCG treatment) NOX4 KO mice group showed reduced tuberculous fibrosis-promoted metastatic potential of lung cancer, increased autophagy, and decreased expression of TGF-β, IL-6, and TNF-α compared to the BCG+KLN205 WT mice group." (PMID 33567693, 2021). "Their in vitro anticancer properties and Tumor necrosis factor alpha (TNF-α-induced) NF-κB activation were evaluated against four human cancer cell lines, such as human ovarian cancer cells (SKOV3), lung cancer cells (A549), liver cancer cells (HepG2), and bladder cancer cells (T24)." (PMID 32824664, 2020). "TNF, EGFR, MYC, IL-6, and JUN were identified as major hub genes of HCT on lung cancer." (PMID 32595734, 2020). "Its expression in lung cancer cells is low, suggesting that lung cancer cells may downregulate CYLD in order to prevent TNF-α induced apoptosis." (PMID 33262947, 2020). "A continuous decrease of serum CEA was observed in 1 patient with lung cancer.Two patients had SD (1 patient with lung cancer).Clinical and immunological responses were only observed in patients treated with adjuvant use of INF-α and TNF-α." (PMID 33679709, 2020). "For example, meroterpenoids, isolated from the brown seaweed Cystoseira usneoides, significantly reduced the production of TNF-α, IL-6, and IL-1β, suppressed COX-2 expression, and displayed higher cytotoxic activities against lung cancer cells compared with normal lung cells." (PMID 33537234, 2020). "Thus, overexpression of TASK-3 in lung cancer cell lines renders these cells resistant to apoptosis induced by TNF, tumor necrosis factor (a mechanism through which cancer cells can defend themselves from the immune system)." (PMID 31810225, 2019). "K-ras activated lung cancer cells orchestrate the TME through secreting cytokines IL-6, IL-10, IL-17, TGF-β, and TNF, which can either suppress antitumor T cells directly or stimulate immune cells such as MDSCs, Th17s, M2 macrophages, and Tregs to inhibit Th1/CD8+ T cell function." (PMID 32039025, 2019). "It has also been shown that TNF neutralization impairs inflammatory cell migration and angiogenesis with an overall decrease in tumor size but not number in a urethane-induced lung cancer mouse model." (PMID 32039025, 2019). "USP17 could be induced by cytokines secreted from macrophages because various cytokines, including TNF-α, IL-1β, IL-4, IL-6, IL-8, IL-10, CXCL12, CCL18, and CCL22, were able to induce USP17 expression in H1299 and D121 lung cancer cells." (PMID 30038267, 2018). "Similar results demonstrating an antagonistic effect of TNF-α over TGF-β2-mediated EMT were obtained in other epithelial cell types studied, like, lung cancer (H1299) and other HCC cell type (HepG2) suggesting a probable universal effect across different cell types." (PMID 29464083, 2018). "Of note, also the expression levels of other putative tumor-derived cachexia-inducing signaling compounds (OSM, LIF, TNFα, IFNγ, PTHrP, ZAG, PIF, TWEAK, IL-1β, MSTN and INHBA) were tested for possible correlation between expression level and prognosis for lung cancer patients." (PMID 28515477, 2017).
lung carcinoma (continued). "Indeed, a previous study has demonstrated that M. pneumoniae infection induces proinflammatory cytokine expression in human lung carcinoma cell line (A549) including IL1β, IL6, IL8, and TNFα." (PMID 28553017, 2017). "The down-regulation of TNFR1 suppressed apoptosis in TNF-α and SAHA-treated lung cancer cells." (PMID 28099148, 2017). "More importantly, a recent study reported that activated macrophages induce TNF-alpha secretion through PPAR-gamma, ERK, and MUC1 signaling and contribute to smoke-induced lung cancer, establishing a direct involvement of MUC1 in TAM and lung cancer." (PMID 27276704, 2016). "Moreover, CYLD-overexpressed lung cancer cells were treated with 10 μM of z-VAD-fmk for 12 hours and the result revealed that TNF-α-induced cell necrosis was significantly enhanced." (PMID 27738385, 2016). "Here, the lung cancer cell line H460 cells were transfected with CYLD-flag plasmid and treated with increasing concentrations (0 ng/mL, 1 ng/mL, 20 ng/mL, and 400 ng/mL) of TNF-α for 24 hours." (PMID 27738385, 2016). "Importantly, MMP9 inhibition decreased the TNF-α- and EGF-stimulated invasiveness of A549 cells, highlighting the importance of the S100A4/MMP9 axis in S100A4-driven invasion in lung cancer cells." (PMID 27127879, 2016). "Our previous studies showed that MMP-13 mediate IL-6 increasing lung cancer metastasis via ATM activation, therefore, we speculate that MMP-13 might be a critical potential target for TNF-α augmenting lung cancer migration." (PMID 27556690, 2016). "Taken together, this suggests that ligand-induced PPARγ sumoylation is specifically involved in the suppression of inflammatory COX2 and TNFα signaling pathways, but not the iNOS pathway, in lung cancer pathogenesis." (PMID 26244663, 2015). "To demonstrate the critical role of the TNF-α/NF-κB/cyclinD1 and IL-6/STAT3/cyclinD1 pathways in the malignant transformation of 16HBE cells, we first detected the expression levels of TNF-α, IL-6, NF-κB, STAT3, and cyclinD1 in lung cancer tissues." (PMID 25823926, 2015). "In this study we have conducted studies directly comparing the effects of RASSF1A and RASSF1C on breast and lung cancer cell proliferation and apoptosis in the presence and absence of TNF-α." (PMID 24327924, 2013). "Therefore, we assessed the phosphorylation of MST1/2 in breast and lung cancer cells overexpressing RASSF1A and RASSF1C in the presence of TNF-α." (PMID 24327924, 2013). "Therefore, we used the TNF-α-induced apoptosis system to compare and contrast the effects of RASSF1A and RASSF1C in breast and lung cancer cells." (PMID 24327924, 2013). "In this study we compared the effects of RASSF1A and RASSF1C overexpression on breast and lung cancer cell proliferation in the presence and absence of TNF-α." (PMID 24327924, 2013). "Monocytes from lung cancer patients produce elevated levels of mature TNF-α which could result from the shedding of pro-TNF-α by ADAM-17 (TACE)." (PMID 16495931, 2006). "Tumour necrosis factor alpha (TNF-α) and transforming growth factor beta (TGF-β) have emerged as two of the many host-derived mediators that seem to interfere with both antiproliferative and tumorigenic effects in malignant tumours including lung cancer." (PMID 10945495, 2000). "Therefore, in this study, we detect the concentrations of TNF-α, IFN-γ, IP-10, MIP-1α, MIP-1β and MIP-2 in collected blood samples from both lung cancer patients and healthy volunteers, to elucidate the potential association between these pyroptosis-related cytokines and lung carcinoma." (PMID 38813211, 2024). "In addition, TNF-α could activate NF-κB pathway in LECs to promote their secretion of CCL21 and promote metastasis and invasion of lung cancer cells through the CCR7-CCL21 axis." (PMID 38566083, 2024).
lung carcinoma (continued). "High expression of the BC-specific ICD-derived metagene signature (TNF/CXCR3/P2RX7/CASP1/NLRP3/IL1B/LY96/CD4+/CD8+A/CD8+B/PRF1/IFNG/IL17A/IL17RA) is associated with prolonged overall survival (OS) in BC and OC patients but not in lung cancer patients." (PMID 37445860, 2023). "TLR4 is specifically shown to help lung cancer cells escape the immune system through the release of immunosuppressive cytokines like transforming growth factor beta (TGF-β), VEGF, and IL-8, while also increasing resistance to proapoptotic factors like tumor necrosis factor-alpha (TNF-α)." (PMID 36389785, 2022). "An orthotopic lung metastatic CMT-167 murine lung cancer model was also tested in syngeneic C57BL/6 mice via lung injection using the same treatment conditions, with the addition of anti-TNF-α antibody to cisplatin leading to significant reduction in lung tumor burden." (PMID 36241629, 2022). "Interestingly, S1P-induced IL-6, but not TNF-α, release from lung cancer-derived PBMCs was mTOR- and K-Ras-dependent, while NF-κB was not involved." (PMID 36010601, 2022). "Therefore, it is not surprising that in the complex process of lung cancer onset, progression, and dissemination, TNFα and its receptors have been reported to play decisive roles, too." (PMID 34445397, 2021). "Hence, LM-DOX could achieve the release of TNF-α release from TAMs and DOX accumulation, leading to a synergetic inhibitory effect against A549 lung cancer cells." (PMID 34834304, 2021). "Finally, an experimental lung cancer metastasis model was used, which was not the same as the TNF-α-induced HUVEC in vitro model." (PMID 32015677, 2020). "Therefore, in this review, we summarized the published literature from the year 2000 to the year 2019, specifically focusing on the role of IL6, TNFα, IL10, CCL2, CX3CL1, IL8 in the macrophages-tumor cells crosstalk; leading to lung cancer development and progression." (PMID 32219066, 2020). "In addition, TNF-α-induced OPN expression in HN-22 cells growing on fibronectin supports occurs via β1 integrin and ERK31; in the present study, OPN was upregulated in SQS-overexpressing cells and correlated with smoking status in lung cancer patients." (PMID 32862200, 2020). "However, the effect of dicentrine on TNF-α-induced apoptosis and metastasis in lung cancer cells has not yet been elucidated." (PMID 31766230, 2019). "In coculture, U937 macrophages have been shown to secrete TNF-α and IL-1α (IL-1α not at high doses) after irradiation of NCI-H446 lung cancer cells with γ-rays (137Cs Source, 8 Gy) but only TNF-α after irradiation with accelerated carbon ions (290 MeV/n, LET 13 keV/μm, 2 Gy)." (PMID 28638385, 2017). "Finally, high TLR9 expression was also observed in both primary lung cancer specimens and tumor cell lines, and activation of the TLR9 pathway resulted in the production of monocyte chemoattractant protein-1 (MCP-1) and the reduction of TNFα-induced apoptosis." (PMID 27733853, 2016). "However, perhaps because these lung cancer cells are not professional phagocytes, we did not observe concomitant up-regulation of TNF expression." (PMID 26270345, 2015). "A combination treatment of tumor necrosis factor (TNF)-like weak inducer of apoptosis, TNF-related apoptosis-inducing ligand, docetaxel and cisplatin, with BV synergistically inhibited both A549 and NCI-H460 lung cancer cell growth with further down regulation of NF-κB activity." (PMID 25068924, 2014). "Considering the abundance of TNFα in the tumor microenvironment, TNFα-induced phosphorylation and degradation of HMGCL might be a mechanism by which tumor cells crosstalk with the microenvironment, and provide novel insights into the tumor-promoting effects of TNFα in the lung cancer." (PMID 36923932, 2023).
lung carcinoma (continued). "In orthotopic lung cancer mice model, LM-DOX could migrate to tumor efficiently in response to CCL2, which facilitated the specific delivery of the encapsulated DOX to tumor cells and the production of TNF-α through activating TAMs by LPS anchored on macrophages." (PMID 34834304, 2021). "Although OTSSP167 inhibited phosphorylated PAK1, we cannot rule out that other activators of PAK1 can intervene in lung cancer, like MLK3 and TNFα." (PMID 31660987, 2019). "Additionally, Nec-1, the RIP-1 inhibitor, also suppressed the apoptosis rate in TNF-α-induced cell necrosis, but it did not affect the expression of RIP-1 in CYLD-overexpressed lung cancer cells." (PMID 27738385, 2016).